AR (androgen receptor)
Diseases named in the same sentence as AR in open-access papers (continued):
Sharing a sentence is not in itself a finding about the gene and the disease.
tumor (continued). "Androgen receptor (AR) signaling remains an important driver of tumor growth even in CRPC." (PMID 33115529, 2020). "One corollary of this hypothesis is that inhibition of the AR variants or their specific function might lead to reversal of EMT phenotype and that might in turn inhibit tumor spread." (PMID 32292603, 2020). "AR and ER expression may co-localize in both, normal and tumor tissues, providing evidence for a possible crosstalk between signaling pathways of these hormone receptors." (PMID 32344660, 2020). "Early methods for assessing tumor clonality used X chromosome-linked studies such as: glucose 6 phosphate dehydrogenase (G6PD); phosphoglycerate kinase (PGK); and a human androgen receptor (HUMARA)." (PMID 32010429, 2020). "While AR and ER share many similarities, there may be important differences determining their role in driving tumor growth." (PMID 33062889, 2020). "Androgens stimulate PCa cells to grow since tumor cells express androgen receptor (AR)." (PMID 33426506, 2020). "Moreover, during androgen-deprivation therapy, cholesterol plays a key role in the de novo androgen synthesis, thus promoting self-sufficiency in AR signaling and hormone-refractory progression of the tumor." (PMID 32085497, 2020). "Additionally, western blot analysis of tumours showed a decrease in AR and ER-α protein expression in the carnosol-treated group." (PMID 33049974, 2020). "Lack of a BRCA mutation, lower tumor grade, and AR expression were all significantly associated with Rb expression." (PMID 32550264, 2020). "Previous studies have mainly focused on AR as a type of nuclear receptor TF that has the ability to promote tumor growth and development by binding to downstream target genes and mediating the activation of genes related to proliferation, anti-apoptosis, or other cancer genes." (PMID 33343635, 2020). "To assess whether these morphologic changes were associated with invasive capability, we evaluated the effects of JQ1 and SP-2509 on tumor invasiveness for AR-positive and AR-negative cell types." (PMID 31901895, 2020). "In most published studies, AR positivity has been defined as ≥10% tumor nuclei staining by IHC." (PMID 32778063, 2020). "Furthermore, AR activities have also been shown to possess a tumour and metastasis suppressor function, suggesting PCa disease progression can be driven by AR‐independent mechanisms." (PMID 32926495, 2020). "Comparison of the clinical and tumor characteristics in function of the tumor AR status showed that tumor size was smaller (p = 0.044), and lymph node involvement was more frequent (47.9% vs. 25%; p = 0.036) in AR+ (n = 107, 72.8%) than with AR− (n = 40, 27.2%) TNBCs." (PMID 32429078, 2020). "Thus, the interaction of AR with ING family members links AR-signaling to ING-tumor suppressor signaling and cell senescence." (PMID 32650419, 2020). "Another study highlighted the importance of Wnt5a expression following AR inhibition by using single-cell RNA sequencing of circulating tumour cells of metastatic PCa patients, and concluded that a subpopulation of PCa cells expresses non-canonical Wnts to enhance their survival." (PMID 32605008, 2020). "Moreover, GSA0932 suppressed AR expression in 22RV1 and VCaP tumor cells after 24h of treatment, reaching its maximal inhibitory activity at a concentration of 3 and 5 μM respectively." (PMID 32477465, 2020). "This panel included the vascular marker CD31, CAF markers (CD34, caveolin-1 (CAV-1) and alpha smooth muscle actin (αSMA)) and steroid hormone receptors (SHR: androgen receptor (AR), progesterone receptor (PR) and estrogen receptor alpha (ERα)) in paired prostate non-tumour (PNT) and PCa tissue." (PMID 33370412, 2020). "In addition, we observed decreased CRPC tumor growth following silencing of CRPC-Lncs along with reduced expression of AR and AR-V7." (PMID 32704143, 2020). "Together, these data suggest that androgens/AR axis may play the potential tumor suppressive role in PTC." (PMID 32365531, 2020).
tumor (continued). "Additionally, decoy peptides with the AR-NTD sequence of AR have been shown to reduce PCa tumor development and serum PSA levels." (PMID 33076388, 2020). "Furthermore, using ChIP-qPCR on PDX tumor tissue, we detected AR, DOT1L and H3K79me2 at this MYC enhancer in addition to the active enhancer marks H3K27ac and H3K4me2 and RNA polymerase II (Pol II)." (PMID 32814769, 2020). "The AR promotes physiological epithelial differentiation, but, in PC, abnormal AR activation can dysregulate the expression of genes involved in the control of proliferation and survival of tumour cells." (PMID 35582226, 2020). "The increased Nkx3.1 expression under arctigenin treatment in this study was concurrent with the decrease in AR expression, and may contribute to the tumor-inhibitory effect of arctigenin." (PMID 31996731, 2020). "Thus, it will also be important to determine if AR+/PSAlow/- PCa patients are predicted to develop CRPCa, show evidence of chronic IL-1-mediated tumor inflammation, and share a common molecular signature with the IL-1 sublines." (PMID 33326447, 2020). "The prognostic effect of AR expression may vary according to the age, menopausal status, and hormonal status of the tumour." (PMID 32928183, 2020). "Nevertheless, men undergoing prior chemotherapy may have greater tumor burden, which attributes to more diverse AR‐independent signaling pathways." (PMID 32374087, 2020). "Finally, the two patients with low ER but high AR pathway activity in the primary tumor showed rapid tumor progression under tamoxifen." (PMID 32230714, 2020). "Moreover, SBR grade was lower (SBR 1–2: 14.1% vs. 2.6%; p = 0.048) and Cath-D expression in tumor cells more frequent (87.3% vs. 72.5%; p = 0.035) in AR+ than AR− tumors." (PMID 32429078, 2020). "On one hand, a tumor suppressive role has been attributed to AR signaling, whereby treatment of AR+ TNBC cell lines with AR agonists inhibited CSC phenotype, decreased EMT by upregulating AR inducible micro RNAs, and inhibited growth of xenograft tumors by modulating paracrine signaling." (PMID 32850312, 2020). "In addition, analysis of the tumor tissues revealed that curcumin treatment reduced AR mRNA and protein levels." (PMID 33182828, 2020). "However, when HER2, ER, and AR were all expressed, the tumor acted with a weak invasive phenotype, and the patient had a superior outcome." (PMID 32982970, 2020). "Interestingly, gene set enrichment analysis and pathway analysis revealed significant downregulation of AR-selective signature genes and enrichment of several neuron differentiation related pathways in shCHD1-XE tumor cell lines." (PMID 32220301, 2020). "Moreover, although pharmacological inhibitors of AR-signaling suppress tumor growth, we and others have shown using in vitro and in vivo approaches that it also promotes invasion of tumor cells." (PMID 32820253, 2020). "AR protein expression in gastrocnemius was low in tumor‐free controls and increased in response to GTx‐024 administration irrespective of tumor burden, consistent with androgen agonist binding and stabilization of the AR." (PMID 31930715, 2020). "Previous studies have revealed that in AR+ TNBC, PIK3CA kinase mutations were more common and that targeting AR alone could potentially enhance tumor growth." (PMID 32982970, 2020). "Furthermore, it exhibits a drastically anti-tumour activity even in castration-resistant cells by disrupting BRD4-mediated androgen receptor (AR) recruitment and transactivation." (PMID 32340605, 2020). "In addition, activated NF-κB upregulates tumour promoting cytokines, leads to increase AR activity in the androgen depletion state." (PMID 32131560, 2020). "Patients resistant to bicalutamide usually can respond to enzalutamide, a second-generation AR antagonist, which has better anti-tumor efficacy than bicalutamide, because of its higher affinity for AR, ability to inhibit nuclear translocation, gene binding, and recruitment of coregulators." (PMID 32982970, 2020).
tumor (continued). "Thus, tumor cells expressing high levels of AR and AR-V7 represent the adenocarcinoma state of prostate cancer, still relying on functional AR axis signaling." (PMID 32685010, 2020). "The underlying mechanisms may include the presence of AR-Vs, differential actions of AR co-regulators, epigenetics, and tumor microenvironment." (PMID 33163409, 2020). "Thus, as a tumor-suppressive molecule, maspin’s anti-tumor activity was further explored to be also through, at least in part, repressing AR expression." (PMID 33195208, 2020). "Enza directly binds to the AR to inhibit its activity and prevent tumor growth." (PMID 32630281, 2020). "A recent study demonstrated that the anatomic location of the tumor in the prostate gland is influenced by AR signaling; tumors situated in the anterior lobe tends to have lower global AR signaling leading to differences in AR molecular subtypes, tumor size, and PSA54." (PMID 31959826, 2020). "Moreover, we detected 15 gene amplifications in six different tumor specimens, including AR, CCND1 (n = 2), FGF19 (n = 2), FGF3 (n =2), KRAS (n = 2), MYC (n = 2), CCND3, CCNE1, CDK6, and RICTOR." (PMID 33203166, 2020). "Furthermore, a more favorable prognostic effect of high levels of CEACAM5 was observed in some sub-clusters of the TN tumor subtype, including Basal-like 1 and Luminal androgen receptor subsets of tumors." (PMID 33196697, 2020). "These divergent results make it difficult to interpret the role of AR in tumor progression." (PMID 33266110, 2020). "On the other hand, PTEN was identified as a negative regulator of AR activity such that the AR/PTEN interaction may mediate a tumor suppressor role for PTEN via suppression of AR and apoptosis induction in PCa cells." (PMID 32292603, 2020). "Hence, to build a progress in PCa therapy, it is essential to understand the detailed mechanisms accounting for anti-androgenic activity and resistance to AR antagonists and consequently to develop other strategies to overcome tumor growth progression." (PMID 32562083, 2020). "Arctigenin intervention significantly reduced tumor growth by 45%, associated with decreased circulating FFAs and adipokines/cytokines including IGF-1, VEGF, and MCP-1, along with decreased AR, Ki67, and microvessel density and increased Nkx3.1 expression in tumors." (PMID 31996731, 2020). "Carbidopa treatment increases AHR protein level and decreases AR protein level in tumor tissues." (PMID 32404918, 2020). "As N-Myc suppresses AR signaling and drives lineage plasticity, tumor aggressiveness, and AR-independent progression in PCa, AURKA interacts with N-Myc through protein-protein interactions (PPI) and forms a complex to protect N-Myc from Fbxw7-mediated proteasomal degradation." (PMID 33167327, 2020). "Furthermore, treatment using estrogen, progesterone and androgen receptor blockade can induce tumor regression." (PMID 32083084, 2020). "Mutated AR often can bypass the need for androgen activation, and can act as transcriptional activator in the absence of androgens, promoting tumor growth." (PMID 32316460, 2020). "Thus, expression of PSMA in combination with AR expression in CTCs seems to be a reliable surrogate for the actual tumor load, reflected by MTV and total lesions." (PMID 32685010, 2020). "AR-pathway activation could also reverse long-term tumour regression by docetaxel treatment in vivo." (PMID 32989230, 2020). "This was similar to other findings in our study, while another study reported a negative association between AR status and tumor grade and invasiveness." (PMID 32104638, 2020). "On immunochemistry, tumor cells are usually positive for AR." (PMID 32042320, 2020). "Therefore, a better understanding of the adaptive tumour phenotype following treatment resistance will help to identify novel therapeutic approaches to tackle AR-proficient CRPC." (PMID 32427840, 2020).
tumor (continued). "The prevalence of AR positivity was lower than most studies in Europe and America which may be a result of regional differences in tumour biology." (PMID 32928183, 2020). "AR can drive tumor growth even in TNBC subtypes expressing low levels of AR." (PMID 33213491, 2020). "In TNBC, it has been suggested that AR activation alters the tumor microenvironment, hence suppressing the antitumor response and upregulating the secretion of the epidermal growth factor receptor (EGFR) ligand amphiregulin (AREG), both stimulating tumor growth and progression." (PMID 33138097, 2020). "The tumours were evaluated in sub-groups based on the menopausal and ER/AR status." (PMID 32928183, 2020). "Together, these findings suggest that either the most aggressive tumor sections were not profiled in Time Point 1, or that subclones with the AR mutation have a proliferative advantage and have overtaken subclones with the EP300 mutation." (PMID 32843649, 2020). "In addition, AR-pathway activation by testosterone stimulated regrowth of docetaxel-treated dormant tumours." (PMID 32989230, 2020). "However, with multivariate analysis, only tumor stage (HR 7.3, 95% CI 1.1–48.35, p = 0.038) and AR expression levels (HR 8.47, 95% CI 1.5–45.5, p = 0.012) were significant predictors of DMFS." (PMID 32778063, 2020). "Currently, it is unclear whether rare subclones originate from the primary tumor or early metastases harbor AR alterations and promote ADT resistance." (PMID 33747899, 2020). "While most studies have shown that AR expression is a good prognostic factor in ER+ tumors, it is more controversial for ER-tumors where AR signaling could drive tumor growth." (PMID 32429078, 2020). "The upregulation of this pathway may contribute to increased proliferation and tumor growth, which is consistent with the established finding that increased AR expression is characteristic of PC patients." (PMID 32899474, 2020). "Thus, oppositional acting ligands, AR antagonists, and agonists are able to induce cellular senescence in PCa cells, as shown in cell culture model as well as ex vivo in patient tumor samples." (PMID 32650419, 2020). "Among 159 tumor specimens analyzed, TILs and AR were evaluable on 151 (94.9%)." (PMID 33208857, 2020). "Furthermore, we found that these two inhibitors exerted different effects on tumor metastasis in cells with distinct extent AR expression." (PMID 31901895, 2020). "In one study using transcriptomic data obtained from TCGA and METABRIC cohorts, high AR levels in ER+ BC correlated with fewer tumor-infiltrating lymphocytes and cytolytic activity, as well as far less sensitivity to neoadjuvant chemotherapy, yet better survival." (PMID 32982970, 2020). "We further evaluated the AHR and AR protein level in these tumor tissues using immunoblot assay." (PMID 32404918, 2020). "Evidence that treatments targeting both the tumor epithelia and the surrounding CAFs can extend the efficacy of conventional chemotherapies is provided by the retinoic acid receptor β and androgen receptor antagonists identified for concurrent therapy with cisplatin." (PMID 32847144, 2020). "In addition to interactions with cyclins and CDKs, AR also interacts with many other important proteins, including well characterized oncogenes and tumor suppressers." (PMID 33062889, 2020). "These tumours respond to RT, retain androgen receptor (AR) expression and sensitivity to androgens, and display an immune ‘cold’ phenotype with tumours being poorly infiltrated by T-cells, and heavily infiltrated with myeloid cells, which is primarily driven by Pten loss." (PMID 33003551, 2020). "Because ESRP plays a critical role in EMT and tumor invasion in several tumor types, we hypothesized that the AR-ESRP axis might be critical for promoting metastasis either by promoting EMT or promoting invasion." (PMID 32820253, 2020).
tumor (continued). "Indeed, AR transcriptional program supports PCa viability during the course from primary tumor formation to progression to metastasis." (PMID 33163409, 2020). "Therefore, a few metastatic BC studies have analyzed AR expression on circulating tumor cells (CTCs) in blood as a minimal invasive approach to assess the real time AR status." (PMID 33014830, 2020). "Multivariate analysis showed female sex (hazard ratio [HR]: 7.360, 95% CI: 1.649–32.856, P = 0.009), tumor size ≥3 cm (HR: 23.697, 95% CI: 4.383–128.117, P < 0.001) and low AR mRNA expression (HR: 0.202, 95% CI: 0.048–0.841, P = 0.028) to be independent predictors of shorter RFS." (PMID 30961575, 2019). "As both Enza and Abi work through AR, the higher AR dependency of the tumor may predict a higher response to AR-targeted drugs." (PMID 30978937, 2019). "However, assessment of the AR-modification status would require representative tumor samples at each time of PSA progression, which is impractical for therapeutic monitoring." (PMID 31289619, 2019). "The frequency of detection of AR, ERα and PR through immunohistochemistry and the immunoreactive score is an estimation of the receptor presence and constitutes a reliable indicator about the endocrine profile of the tumor." (PMID 30736825, 2019). "The AKT, c-Myc, and AR are all essential for tumor growth and progression of PCa." (PMID 31766290, 2019). "Thus, the dual inhibitor NEO2734 can inhibit the activation of both AKT and AR signaling in Q165P mutated PCa PDX tumors, resulting in the suppression of tumor growth in vivo." (PMID 31559706, 2019). "However, considering the opposite effects of AR blockade in tumor and stromal cells, an ideal anti-androgenic agent should decrease tumor AR but enhance stromal AR activity." (PMID 30925918, 2019). "Similarly to CCND1, expression of the cell cycle-related genes RB1 (retinoblastoma 1) and AR (androgen receptor) were also higher in luminal tumours relative to basal-like (see “AR” and “RB1”, P < 0.001 for luminal A vs. basal-like comparisons)." (PMID 30819233, 2019). "Interestingly, DDX5, but not DDX17, affect key cellular pathways, including upregulation of AR in PCa and induction of epithelial-mesenchymal transition (EMT), a feature that is associated with tumor invasion capabilities." (PMID 31164793, 2019). "Moreover, the involvement of AR in the tumor aggressiveness is also highlighted by the correlation between AR and cNHERF1, a marker of tumor progression in BCs, and involved in different signaling pathway." (PMID 31540486, 2019). "Recent studies identify that ARv567es actively transcribes a unique set of target genes that are distinct from full length-AR, indicating that expression of ARv567es could be a fail-safe mechanism used by tumor cells to promote cell survival." (PMID 31771198, 2019). "Multivariate analysis showed that female sex (HR: 7.360, 95% CI: 1.649–32.856, P = 0.009), tumor size ≥3 cm (HR: 23.697, 95% CI: 4.383–128.117, P < 0.001) and low AR mRNA expression (HR: 0.202, 95% CI: 0.048–0.841, P = 0.028) were independent predictors of shorter RFS." (PMID 30961575, 2019). "Whereas AR and ER-α have a quite similar structure and are co-expressed by many BCs, the role of AR may be different depending on the levels of both hormone receptors in the tumor environment." (PMID 30941159, 2019). "The majority of the studies in the literature have relied upon IHC to assess tumor AR status." (PMID 31840050, 2019). "However, PCa cells express high levels of the AR with excess activation of AR signaling pathways, which enhances cellular proliferation and tumor formation." (PMID 31181727, 2019). "Given their effects on AR activity, we examined phenotypic consequences using proliferation assays and found that miR-346 and -361-3p inhibitors reduce proliferation, supporting a tumour-promoting/oncogenic effect of the corresponding miRs." (PMID 31043708, 2019).